C11orf24 (chromosome 11 open reading frame 24)
Synonyms: DM4E3
Tractability: Antibody: UniProt places it where antibodies can reach, with high confidence; UniProt predicts a signal peptide or a membrane-spanning region; its Gene Ontology location is reachable by antibodies, with medium confidence.
Gene: Protein-coding gene on chromosome 11 (68,261,335 to 68,272,001, reverse strand). Ensembl gene ENSG00000171067.
Subcellular location: Cell membrane; Golgi apparatus, trans-Golgi network membrane
Subcellular location (Human Protein Atlas): Golgi apparatus; Nucleoplasm; Vesicles
Gene Ontology:
Molecular function: protein binding
Cellular component: Golgi apparatus; plasma membrane
Genetic constraint (gnomAD): Loss-of-function variants: 5 observed, 8.98 expected, observed/expected ratio (o/e) 0.56, 90% interval 0.29 to 1.17. That is too few expected variants to judge how well the gene tolerates losing a copy. Missense variants: 566 observed, 622.97 expected, observed/expected ratio (o/e) 0.91, 90% interval 0.85 to 0.97. Synonymous variants: 233 observed, 247.89 expected, observed/expected ratio (o/e) 0.94, 90% interval 0.84 to 1.05.
Homologues: Orthologues: chimpanzee C11H11orf24 (97% identical), macaque C14H11orf24 (75% identical), rat C1h11orf24 (48% identical), mouse 1810055G02Rik (47% identical), dog C18H11orf24 (45% identical), tropical clawed frog c4h11orf24 (24% identical). Paralogues in human: MANSC1 (16% identical), MANSC4 (8% identical).